INS (insulin)
Diseases named in the same sentence as INS in open-access papers (continued):
Sharing a sentence is not in itself a finding about the gene and the disease.
Insulin resistance (continued). "When we instead analyzed the change in IAPP concentration between baseline and after 3 months of diet (changes further on), we again noted a positive correlation with BMI as well as insulin and insulin resistance, glucose, and several interleukins, but a negative correlation with NfL." (PMID 39062913, 2024). "Whether this acute stimulatory effect of AA on insulin is conserved over time, as well as whether this is desirable knowing the effect of chronic hyperinsulinemia on worsening of insulin resistance, needs to be established." (PMID 39114126, 2024). "Insulin resistance is a disease classified by the resistance of cells to the function of insulin and may lead to the development of type 2 diabetes (T2DM) and heart disease." (PMID 38474713, 2024). "Additionally, inflammatory processes play important roles in the pathophysiology of obesity, insulin resistance (IR) and the modulation of insulin signaling." (PMID 39324112, 2024). "With insulin resistance playing a major role in the pathogenesis of MetS, repurposing insulin sensitizers and incretins glucagon-like-peptide-1 receptor (GLP-1R)-agonists has become an accepted therapeutic strategy, particularly at the early stages of the disease." (PMID 39640841, 2024). "As a result, vaspin could play a protective role in obesity because of its connection to insulin resistance via its insulin-sensitizing and anti-inflammatory effects." (PMID 39519480, 2024). "Background/Objectives: The aim of this study was to investigate the feasibility and practicability of repeated three-day sequences of a hypocaloric oat-based nutrition intervention (OI) in insulin-treated outpatients with type 2 diabetes and severe insulin resistance." (PMID 39274338, 2024). "Insulin resistance is defined as the body having an impaired response to insulin." (PMID 38255204, 2024). "Also, excessive insulin signaling, e.g., in insulin resistance, has been demonstrated to increase inflammation and promote aging further." (PMID 37980298, 2024). "Through crosstalk with adipose tissue, skeletal muscle and the liver metabokines and lipokines play crucial roles in regulating energy metabolism and insulin sensitivity, and thus might influence the pathogenesis of obesity and insulin resistance." (PMID 39591977, 2024). "Hyperglycemia in type 2 diabetes (T2DM) may occur as a result of insulin resistance and inappropriate insulin secretion, and glycemic control can be achieved by administering insulin in an appropriate dose." (PMID 39594627, 2024). "Fasting insulin (FI) is a crucial marker of insulin resistance." (PMID 38771888, 2024). "In addition, it has been further suggested that hyperinsulinemia-induced insulin resistance can be considered an adaptive response of the body to maintain normoglycemia and prevent hypoglycemia in the presence of high insulin levels." (PMID 38791525, 2024). "This is in agreement with a large body of evidence indicating metabolic inflexibility in response to different metabolic and physiological challenges (e.g., insulin stimulation, varying dietary compositions, exercise) in obesity, insulin resistance, metabolic syndrome, and type 2 diabetes." (PMID 38416072, 2024). "During pregnancy, insulin resistance and impaired insulin secretion may lead to the development of Gestational Diabetes Mellitus (GDM)." (PMID 38863517, 2024). "Scopolamine improves insulin resistance and promotes insulin secretion." (PMID 38802644, 2024). "Additionally, insulin sensitivity and the homeostatic model assessment of insulin resistance (HOMA-IR) were found to be elevated in BoNT/BTan mice compared to control mice, indicating a prediabetic, insulin-resistant state in BoNT/BTan overweight mice." (PMID 39047908, 2024). "Insulin sensitivity (or insulin resistance) may be quantified using “gold standard” methods such as the euglycemic-hyperinsulinemic clamp (EHC), or through the minimal model analysis of a frequently sampled intravenous glucose tolerance test." (PMID 38473112, 2024).
Insulin resistance (continued). "Furthermore, individuals with T2DM dealing with chronic insulin resistance have been found to have reduced oxidation of glucose and insulin-stimulated muscle glycogen synthesis." (PMID 39807459, 2024). "Adjunctive therapy with GLP-1RA alongside insulin may provide direct and indirect benefits by increasing glucagon and reducing insulin resistance in patients with T1DM." (PMID 38962634, 2024). "Moreover, male mice on WD clearly exhibited insulin resistance, while WD-fed females only showed significantly higher glucose levels 15 min after insulin administration." (PMID 38814444, 2024). "Despite many studies demonstrating the correlation between BCAAs and insulin resistance, valine was reported not to cause insulin sensitivity or worsen insulin resistance." (PMID 38093456, 2024). "Thus, they showed that an initial defect in insulin secretion leading to hyperglycemia can result in the development of skeletal muscle insulin resistance." (PMID 38426504, 2024). "Our working hypothesis underscores the conceivable role of PD-1+CD4 Tconv cells in effecting an inter-organ propagation of a proinflammatory milieu, thereby contributing to insulin resistance across various insulin-sensitive tissues." (PMID 38380252, 2024). "Furthermore, MK-2206 and AZD5363 inhibitors target AKT which is a key protein in the insulin signaling pathway that can lead to insulin resistance." (PMID 39410536, 2024). "Insulin resistance in adipocytes can impair central insulin action, which is involved in cognitive processes and energy and glucose homeostasis in the brain, and could thereby increase vulnerability to amyloid toxicity and oxidative stress." (PMID 38664832, 2024). "In addition, 3 SNPs located on this gene have been associated with type II diabetes mellitus, fasting blood glucose and insulin measurements, as well as with insulin resistance (HOMA-B) in recent GWAS." (PMID 38419113, 2024). "Furthermore, administration of exogenous SCGN has been found to enhance insulin signaling pathway activity, consequently alleviating insulin resistance." (PMID 39068218, 2024). "However, female SD mice demonstrated insulin resistance, and the level of blood glucose was higher at 120 min after insulin injection in the SD mice as compared to the Ctrl mice (B’), consistent with the results of the OGTT." (PMID 38393018, 2024). "Here, we show that increasing ISR signaling with HF, an orally available activator of GCN2 that has progressed to phase 2 clinical trials for various indications, reduced glucose intolerance, weight gain, insulin resistance, and serum insulin levels in DIO mice." (PMID 39150520, 2024). "Quercetin has been effective in guarding against oxidative stress, supporting the regeneration of pancreatic β-cells, improving insulin secretion, and reducing insulin resistance, and restored normal endothelial function in diabetic rats when used in conjunction with metformin." (PMID 38465879, 2024). "However, in subjects with insulin resistance, insulin administration can also induce pro-atherosclerotic effects, such as increased macrophage activation." (PMID 39407846, 2024). "Insulin has an anabolic effect on the bone, so the finding of lower OC in T2D could be related to the insulin resistance which is characteristic of these patients." (PMID 38634086, 2024). "Insulin resistance (IR) is a common pathological state in which insulin-dependent cells, such as adipocytes and cardiomyocytes, are impaired in their ability to respond to insulin." (PMID 38783200, 2024). "Disturbance in the homeostasis of specific trace elements may impact both glucose and insulin metabolism and increase oxidative stress reactions, which may further lead to insulin resistance development." (PMID 39685901, 2024).
Insulin resistance (continued). "In conclusion, our data suggest that higher serum myostatin levels are associated with lower insulin sensitivity in otherwise healthy adults, age 20–65 years, with overweight/obesity, independent of other risk factors for insulin resistance." (PMID 39261976, 2024). "Furthermore, a recent study conducted in Korea involving over 4000 participants found an inverse relationship between insulin levels, insulin resistance, and the dietary intake of flavonols and flavones." (PMID 38667785, 2024). "However, 25(OH)D level was independently associated with liver fibrosis even when adjusted for age, sex, body mass index, hemoglobin A1c, insulin, and homeostatic model assessment of insulin resistance (OR = 0.964 [0.935-0.993], P = 0.015)." (PMID 39698035, 2024). "This enhanced insulin sensitivity may reduce insulin resistance in the heart, thereby improving cardiac function and offering potential cardioprotective effects." (PMID 39337658, 2024). "Although all eight men with type 2 diabetes displayed a significantly higher HOMA-IR than men with NGT, suggesting the presence of insulin resistance, myotubes from three men with type 2 diabetes responded surprisingly well to insulin, as their glycogen synthesis was increased by 2.0- to 2.5-fold." (PMID 38814443, 2024). "When insulin resistance occurs, insulin function becomes hyperactive, but as long as the DI index remains within the appropriate range, the risk of HUA might not increase." (PMID 38172728, 2024). "Finally, in a study of 7633 Chinese men, patients with insulin resistance were found to exhibit both higher insulin levels and lower Lp(a) levels." (PMID 39210428, 2024). "Indeed, BAT plays a crucial role in regulating glucose homeostasis and enhancing insulin sensitivity, whereas brown adipogenesis is notably suppressed in individuals with insulin resistance." (PMID 39796338, 2024). "Additionally, insulin resistance or insufficient insulin secretion further suppresses osteoblast function, leading to decreased bone formation." (PMID 39944232, 2024). "However, perceiving normal pregnancy as a relatively insulin resistant state, the concept of insulin resistance remained our focus and furthermore, the available register data did not allow for further elucidation of the heterogeneous condition." (PMID 39497166, 2024). "A lack of insulin sensitivity and insulin resistance are partially caused by the alteration of various physiological factors of insulin regulation." (PMID 38255955, 2024). "Meanwhile, oxidative stress could induce production of inflammatory mediators, gradually impairing β-cell function, reducing insulin sensitivity, and increasing insulin resistance, all of which result in GDM." (PMID 39035682, 2024). "Notably, PA (P-32:2) was the sole lipid that exhibited correlations with TG concentration and insulin and Homeostatic Model Assessment of Insulin Resistance (HOMA-IR) levels." (PMID 38932852, 2024). "The pancreas is unable to produce enough insulin to overcome insulin resistance." (PMID 39768947, 2024). "Laurate-bioconjugated fructans reduced food and energy intake, body weight, body mass index, abdominal circumference, adipose tissue, adipocyte area, serum triglycerides, insulin, insulin resistance, and C-reactive protein but they increased IL-10 protein serum levels and mRNA expression." (PMID 39204141, 2024). "However, it is unclear if this relationship reflects a positive effect of insulin on BMI as, conversely, hyperinsulinaemia is typically interpreted as a marker of insulin resistance." (PMID 39174749, 2024). "Furthermore, one of the most important mechanisms contributing to reduced insulin sensitivity, at both systemic and tissue levels, is inflammation, which together with insulin resistance forms a vicious cycle in which each condition promotes the other." (PMID 39268230, 2024). "The production of these inflammatory factors may decrease hepatic sensitivity to insulin, leading to insulin resistance." (PMID 38996156, 2024).
Insulin resistance (continued). "Elevated glucose levels and insufficient insulin could both contribute to the development of insulin resistance and hypertension." (PMID 39607203, 2024). "This biguanide increases insulin sensitivity and in cases of hypercortisolemia, whereas a significant number of patients have both hyperglycaemia and insulin resistance, so this might be helpful as a first-line therapy." (PMID 39062179, 2024). "As an insulin sensitizer, metformin could act principally to ameliorate neuronal insulin resistance, a characteristic of Alzheimer disease." (PMID 39434474, 2024). "Furthermore, the placenta is a source of a large number of adipokines that regulate insulin action and insulin resistance." (PMID 39057684, 2024). "Although GLV intake is negatively correlated with NAFLD in normal/overweight individuals, obesity-related metabolic complications such as hyperlipidemia and insulin resistance may significantly increase liver lipids, resulting in decreased insulin sensitivity." (PMID 38974809, 2024). "It follows that non-insulin dependent glucose lowering interventions, such as exercise, may be a necessary part of reversing insulin resistance while managing glucose levels." (PMID 38572086, 2024). "However, in the prediabetic state, there is elevated glucose concentration, insulin secretion, HbA1c, and preliminary insulin resistance compared to glucose-tolerant individuals." (PMID 38612885, 2024). "Dysfunction in insulin signaling during pregnancy, which can result in chronic insulin resistance, is also thought to play a role in GDM; clinical research has found that the rate of insulin-stimulated glucose uptake in GDM patients is less than half of that in normoglycemic pregnant patients." (PMID 38339106, 2024). "Notably, HOMA-IR, a widely utilized index for assessing insulin resistance, relies on glucose and insulin levels obtained during fasting." (PMID 39224613, 2024). "Therefore, treatment for children with obesity is comprehensive and multifaceted, aiming to cultivate a healthy lifestyle that can effectively improve insulin resistance and enhance insulin sensitivity." (PMID 40302954, 2024). "There is also evidence that altered relations of copeptin with insulin may be an indicator of developing insulin resistance." (PMID 39769071, 2024). "Our longitudinal analysis of cardiometabolic risk factors showed that baseline leucine, valine, and tyrosine were predictors of two-year change increases in insulin concentration, whereas tyrosine was also a predictor of deteriorating insulin resistance over time (HOMA-IR)." (PMID 39125441, 2024). "Mechanistically, NOD1 disrupts insulin signaling and mediates insulin resistance." (PMID 39906040, 2024). "Insulin resistance refers to the target organs of insulin action, such as liver, muscle and other reduced sensitivity to insulin action, and the normal physiological response of insulin cannot be performed." (PMID 38633237, 2024). "Second, from the time of T2DM diagnosis, various other factors such as medication and lifestyle changes (dietary changes, weight loss, increased physical activity) may influence the degree of insulin resistance and consequently serum levels of insulin." (PMID 38492115, 2024). "The skeletal muscle plays a critical role in insulin-stimulated glucose uptake, and changes in skeletal muscle DNA methylation by antipsychotics may play a role in the development of insulin resistance." (PMID 38791018, 2024). "A reduction in leptin levels may indicate improved leptin sensitivity, which could reduce inflammation and insulin resistance, thereby restoring metabolic balance and supporting beneficial outcomes in insulin sensitivity and lipid metabolism." (PMID 39770882, 2024).
Insulin resistance (continued). "Insulin resistance dampens glucose uptake, leading to hyperglycaemia, which, as already described, is initially compensated by an insulin hypersecretory response by the pancreatic β-cells, leading to hyperinsulinemia, which precedes the onset of full-blown T2DM and characterises prediabetes." (PMID 39408212, 2024). "We assessed whether the IGI and Index60 can be used to adjust for HOMA-IR and Matsuda Index in examining the roles of insulin resistance and insulin sensitivity in the pathogenesis of type 1 diabetes." (PMID 37914981, 2024). "This is in agreement with our findings that the F/B ratio was reduced and Bacteroidetes was increased, which resulted in decreased serum insulin and Homeostatic Model Assessment of Insulin Resistance (HOMA-IR) levels and enhanced insulin sensitivity after herbal intervention." (PMID 39451562, 2024). "In contrast, continuous measures of body mass index, blood pressure, insulin secretion and insulin resistance were useful in identifying those likely to have the largest improvements in glycaemic control and cardiovascular risk factors by adding semaglutide or dapagliflozin." (PMID 38177805, 2024). "The majority of DM patients are classified into two primary categories: Type 1 DM (T1DM), caused by an absolute or a near absolute deficiency of insulin, or Type 2 DM (T2DM), characterized by insulin resistance with an inadequate compensatory increase in insulin secretion." (PMID 39064398, 2024). "Furthermore, the potential link between AD and brain insulin resistance has made insulin sensitizers like metformin a focus in AD treatment." (PMID 38595695, 2024). "Metabolic and inflammatory mechanisms contribute to the development of MASH,2,3 with insulin resistance playing a significant role in the pathogenesis of the disease, as reflected by a reduced hepatic, whole body, and adipose tissue insulin sensitivity in this patient population." (PMID 39131144, 2024). "Adiponectin improves insulin resistance and protects β-cells by increasing insulin sensitivity." (PMID 39272484, 2024). "Mechanisms linking brain insulin resistance and AD include hyperinsulinemia; the competition between insulin-degrading enzymes and βA; the binding of βA to insulin receptors, impairing signaling pathways; and the downregulation of insulin receptors due to βA binding." (PMID 39273520, 2024). "Selective insulin resistance in the liver, according to another hypothesis, may be due to insulin-independent lipogenesis." (PMID 38397072, 2024). "Insulin resistance is defined as a state in which insulin action is reduced." (PMID 39803116, 2024). "Since glucagon stimulates insulin release and increases hepatic glucose production, hyperglucagonaemia may contribute to the enhanced β-cell responsiveness and insulin resistance known to characterize early-onset type 2 diabetes (T2D)." (PMID 39459592, 2024). "In this study, we explored the multifaceted role of RG saponin, derived from Korean Red Ginseng, in modulating mitochondrial dynamics, oxidative stress, and insulin signaling pathways, which are pivotal in the pathogenesis of insulin resistance and metabolic disorders." (PMID 38998642, 2024). "Fasting and post-OGTT plasma glucose concentrations declined by 33 and 73 mg/dL, respectively; insulin secretion (Δ C-Pep0–120/Δ G0–120) increased 2-fold; and β cell function (disposition index) (Δ C-Pep0–120/Δ G0–120/insulin resistance) rose 2.4-fold, where C-Pep is C-Peptide and G is glucose." (PMID 38426504, 2024). "These outcomes collectively demonstrate that ginseng extract could promote insulin secretion, suppress glucagon secretion, improve pancreatic islet function, and ameliorate insulin resistance in T2DM mice." (PMID 38989151, 2024).